CXCR4 (C-X-C motif chemokine receptor 4)
Diseases named in the same sentence as CXCR4 in open-access papers (continued):
Sharing a sentence is not in itself a finding about the gene and the disease.
HCMV infection (9 papers, 2012 to 2024). "In contrast, using a TB40E strain lacking the US28 gene we detected that CXCR4 downregulation is strongly impaired, in particular at late times after infection indicating an important role of US28 for CXCR4 modulation during the course of HCMV infection." (PMID 27955674, 2016). "Data not shown) interestingly, the impaired migration seen following HCMV infection was more dramatic than that seen following neutralization of CXCR4." (PMID 23116176, 2012). "HCMV infection also upregulated mRNA expression of both CXCR4 and CXCR7; however, protein expression levels of both chemokine receptors were unaffected by HCMV infection." (PMID 23116176, 2012). "We show a differential regulation of CCR7 and CXCR4 upon HCMV infection of mDCs." (PMID 28484459, 2017). "Blockade of CXCR4 function with a neutralizing antibody (12G5) partially inhibited migration and invasion toward CXCL12, but to a lesser extent than the inhibition seen following HCMV infection, suggesting that both CXCR4 and CXCR7 may mediate migration and invasion in response to CXCL12." (PMID 23116176, 2012). "Instead, the individually infected cells exhibited a lower CXCR4 induction, peaking at 4 d.p.i. in HHV-6A infection (21.04-fold) and at 10 d.p.i. in HCMV infection (123.08-fold)." (PMID 36014018, 2022). "In particular, HCMV infection led mainly to the over-expression of CCL2, CCL3, CCL11, CXCR4, IL-1β, IL13, MMP1, MMP3, MMP9 and MMP13, SERPINA1, TNFα, and BMP7, and the gradual and constant downregulation of IL13RA2 (up to almost 800-fold at 14 days p.i.)." (PMID 32899126, 2020). "Network analysis of the differentially expressed genes in cord DCs, revealed among the downregulated genes after 16 h of HCMV infection several GPCRs with pro-inflammatory response function (ADORA3, ARRB1, C5AR1, CXCR4, GPR34, GPR183, GRK3, and RGS18)." (PMID 28993767, 2017). "Given perinuclear sequestration and decreased secretion of CXCL12 following HCMV infection of SGHPL-4 cells, the abundance and distribution of the CXCL12 receptors, CXCR4 and CXCR7, were also analyzed." (PMID 23116176, 2012). "HCMV infection significantly increased mRNA and total cell surface expression of the two known receptors for CXCL12: CXCR4 and CXCR7." (PMID 23116176, 2012). "The effect of HCMV infection on expression of the CXCL12 receptors, CXCR4 and CXCR7, was also investigated." (PMID 23116176, 2012). "The aim of this study was to determine the effect of HCMV infection on cellular distribution and expression of CXCL12 and its receptors, CXCR4 and CXCR7, and on EVT migration and invasion in response to CXCL12." (PMID 23116176, 2012). "Despite recruitment of CXCR4 and CXCR7 to the cell membrane, both migration and invasion toward CXCL12 were almost completely inhibited following HCMV infection." (PMID 23116176, 2012). "Although we took advantage of existing murine fibroblasts that expressed αFAP-tagged human CXCR4 for this study, FAP-tagged receptors can also be expressed in a variety of cell types that are more relevant to HCMV infection, such as human epithelial cells and monocytes." (PMID 28207860, 2017). "Given the upregulation of surface and mRNA expression of CXCR4 and CXCR7 following HCMV infection, it seemed likely that total protein levels may likewise be increased." (PMID 23116176, 2012). "In addition to these, HCMV infection of cord DCs resulted in a suppression of several other GPCRs [including GPR68, GPR183 (EBI2), and GPR146] that, together with C5AR1, CXCR4, and RGS18, have been shown to be highly enriched in unstimulated macrophages and dendritic cells." (PMID 28993767, 2017). "Some receptors, for instance, CD97 and CD184 (CXCR4), were not further validated, since they showed differential effects upon HCMV infection of macrophages from different donors." (PMID 34399625, 2021).
HCMV infection (continued). "Given the decreased secretion of CXCL12 following HCMV infection of SGHPL-4 cells, it is possible that HCMV-infected cells upregulate cell surface and mRNA expression of CXCR4 and CXCR7 as an attempt to compensate for lack of or dysregulated autocrine signaling." (PMID 23116176, 2012).
Hypertension (9 papers, 2015 to 2025). The presence of chronic increased pressure in the systemic arterial system. "Although in that study these observations were associated with marked hypertension, which was mitigated by CXCR4 antagonism, the current study demonstrates that the anti-fibrotic effects of CXCR4 antagonism are not blood pressure dependent." (PMID 26214690, 2015). "The literature mainly highlights the receptors CCR2, CCR5, CXCR1, CXCR2, and CXCR4 as the most relevant for the progression of hypertension." (PMID 40859641, 2025). "We also previously showed that selective CXCR4 antagonism attenuated the development of cardiac fibrosis in experimental hypertension." (PMID 30837882, 2019). "Of note, several of these genes (Cx43, Myh7, CSF1R, CXCR4, and CACNA1) have been reported to be associated with AF, hypertension, inflammation, cardiac and vascular remodeling." (PMID 31191333, 2019). "Furthermore, it has been demonstrated that activation of the SDF1/CXCR4 axis can be pro-fibrotic and pro-inflammatory in experimental models of lung injury and hypertension." (PMID 30837882, 2019). "ANO6, CXCR4, and HIF1A were significant also after adjustment for baseline variables showing an imbalance between STEMI and NSTEMI groups (age, hypercholesterolemia, hypertension, aspirin and statin use, time-to-presentation, admission cTnI)." (PMID 32457432, 2020). "Due to the limited follow-up period, we could not evaluate the value of CXCR4 PET/CT in predicting hypertension recurrence after adrenalectomy." (PMID 40246740, 2025).
idiopathic pulmonary fibrosis (9 papers, 2014 to 2025). Idiopathic pulmonary fibrosis (IPF) is a nonneoplastic pulmonary disease that is characterized by the formation of scar tissue within the lungs in the absence of any known cause. "Another highly relevant clinical application of CXCR4-targeted inflammation imaging is the non-invasive assessment of disease activity in idiopathic pulmonary fibrosis (IPF)." (PMID 34885030, 2021).
latent infection (9 papers, 2009 to 2023). "For example, HIV-1 binding to the chemokine coreceptor CXCR4 or CCR5 has been shown to trigger G-protein signaling critical for HIV latent infection of blood resting CD4 T cells." (PMID 34765923, 2021). "Prestimulation of resting CD4 T cells with an anti-CXCR4 antibody has been shown to trigger cofilin activation that enhances HIV-1 latent infection of resting T cells." (PMID 34765923, 2021). "During HIV latent infection, cofilin is activated by gp120 binding to CXCR4/CCR5 on the surface of resting T cells." (PMID 34447368, 2021). "Using the CCL19 model of HIV latency, we found that in up to 50% of donors, CCL19 enhanced latent infection of resting CD4+ T-cells by CXCR4-tropic HIV in the presence of low dose IL-2." (PMID 27383184, 2016). "Recently, we examined the requirement for CXCR4 signaling in HIV-1 latent infection of human resting CD4 T cells using an in vitro system to mimic in vivo latent infection of resting T cells." (PMID 20041213, 2009). "Recently, we demonstrated a unique requirement for CXCR4 signaling in HIV latent infection of blood resting CD4 T cells." (PMID 19851458, 2009). "Using this system, we observed an absolute requirement of CXCR4 signaling for HIV-1 latent infection of resting CD4 T cells." (PMID 20041213, 2009). "In particular, signals transduced from the chemokine coreceptor CXCR4 have recently been shown to be essential for HIV-1 latent infection of resting CD4 T cells." (PMID 19851458, 2009). "However, we also found that CXCR4 was inhibited during latent infection in PBMCs, and resulted in inhibition of the lytic state and viral replication." (PMID 36272970, 2022). "Prestimulation of resting CD4 T cells with anti-CXCR4 antibody enhances HIV-1 latent infection of resting CD4 T cells; it has been shown that such stimulation leads to the activation of cofilin and localized actin activities, thereby facilitating viral entry and nuclear migration." (PMID 34765923, 2021). "In contrast, prestimulation of CXCR4 enhanced HIV-1 latent infection, as previously reported." (PMID 34765923, 2021). "CXCR4 expression induced by LMP2A could not only contribute to cell growth but also persistently induce EBV latent infection in EBVaGC." (PMID 33052232, 2020). "CXCR4-LTR co-expression presents a risk for latency reversal as certain LRAs could induce cell migration to SDF-1α-rich areas by over-expression of CXCR4, where uninfected cells could potentially become the target of new active and latent infections." (PMID 34201394, 2021). "Therefore, CXCR4 may play an important role in maintaining EBV latent infection in EBVaGC development." (PMID 33052232, 2020). "HIV is an extremely harmful virus, HIV mainly infects a variety of immune cells with CD4+ T and chemokine receptors CXCR4/CCR5 on their surface, making them in a latent infection state." (PMID 37108519, 2023). "In contrast to CD2 signaling, prestimulation of resting CD4 T cells with anti-CXCR4 antibody, with the chemokines CCL19/CCL21, or with IP-10 (CXCL10) has been shown to promote HIV-1 latent infection of resting CD4 T cells." (PMID 34765923, 2021). "IP-10 has been found to activate the cofilin pathway and promote HIV latent infection of resting memory CD4 T cells, likely by a similar mechanism through synergizing with HIV-mediated CXCR4 signaling." (PMID 34765923, 2021). "Increasing the infectious titre of CXCR4-tropic HIV increased both productive and latent infection of resting CD4+ T-cells." (PMID 27383184, 2016). "Previously, we demonstrated a critical function of the HIV-1 envelope in mediating CXCR4 signaling and promoting the cortical actin dynamics necessary for HIV latent infection of resting T cells." (PMID 19851458, 2009).
latent infection (continued). "Given the opposite effects of CXCR4 and CD2 prestimulation on HIV-1 latent infection we speculated that CD2-initiated cofilin and actin polymerization may spatially compete with the HIV-1/CXCR4-initiated cofilin and actin activity that is needed for viral entry and nuclear migration." (PMID 34765923, 2021).
myelodysplastic syndrome (9 papers, 2014 to 2022). A clonal hematopoietic disorder characterized by dysplasia and ineffective hematopoiesis in one or more of the hematopoietic cell lines. "Interestingly, studies on the expansion of MDSCs in the context of myelodysplastic syndrome (MDS), showed a high membrane expression of CX3CR1 and CXCR4 on patients MDSCs compared to healthy controls and that these levels were correlated with patients’ risk stratification." (PMID 33922612, 2021).
synovial sarcoma (9 papers, 2015 to 2024). "In synovial sarcomas in the post-neoadjuvant setting, we observed that cytoplasmic CXCR4 was associated with survival." (PMID 38893721, 2024). "Interestingly, positive CXCR4 nuclear staining was significantly associated with poor survival in a cohort of 80 synovial sarcoma cases." (PMID 34440844, 2021). "Our findings strengthen the importance of CXCR4 in STSs as a prognostic factor in some histological subtypes such as synovial sarcomas and UPS, suggesting a new line of research toward a therapeutic approach." (PMID 38893721, 2024). "In synovial sarcoma, cancer stem cells expressing CXCR4 have been shown to have tumor initiation and self-renewal capacity." (PMID 38893721, 2024). "CXCR4, involved in tumour development and metastatic spread in a variety of cancers, as well as synovial sarcoma cell migration and invasion, has been identified as a potential target of miR-494-3p." (PMID 36765536, 2023). "In synovial sarcoma, CXCR4 mRNA and protein expression levels are upregulated in tumor as compared to non-tumor tissues." (PMID 34440844, 2021). "Chemokine receptor type-4 (CXCR4) has been described to be overexpressed in synovial sarcoma (SS), where the CXCR4+ cells have been outlined to have a higher tumor initiation potential in in vivo experiments and a higher sphere formation capacity." (PMID 32532153, 2020). "CXCR4 has a pivotal role in the migration of cancer cells between the primary and the metastatic site in synovial sarcoma." (PMID 28191313, 2017). "We found that a positive cytoplasmatic expression of CXCR4 in tumors after neoadjuvant treatment was a predictor of poor recurrence-free survival (RFS) (p = 0.003) and overall survival (p = 0.019) in synovial sarcomas." (PMID 38893721, 2024). "In metastatic tumour samples of synovial sarcoma, downregulation of miR-494-3p and increased expression of its potential target CXCR4 were more pronounced than in non-metastatic tumours and healthy tissues." (PMID 36765536, 2023). "Thus, synovial sarcoma and UPS patients whose tumors express CXCR4 may benefit the most from the development of CXCR4-targeted therapies and/or intensive surveillance." (PMID 38893721, 2024). "Patients with synovial sarcomas (N = 9) that expressed cytoplasmatic CXCR4 in surgical biopsies after neoadjuvant treatment showed unfavorable RFS [17.3 months (95% CI: 7.22–27.40) in positive CXCR4 versus not reached in negative CXCR4; p = 0.003]." (PMID 38893721, 2024).
T-cell leukemia (9 papers, 2014 to 2022). A malignant disease of the T-lymphocytes in the bone marrow, thymus, and/or blood. "All papers so far evidenced that targeting CXCR4 in Notch-induced T-ALL reduces tumor growth and BM infiltration in the animal models, suggesting the central role of CXCR4 in Notch-triggered T-cell leukemia progression." (PMID 31346528, 2019). "The Jurkat T cell leukemia line, which expresses high levels of CXCR4, was incubated with CXCL12 (EC80 at 8 nM) to stimulate calcium flux." (PMID 28526063, 2017). "The CXCR4 receptor affinities of the cold reference compounds were determined in competitive binding assays using CXCR4-expressing Jurkat T - cell leukemia cells and [125I]FC131 as the radioligand." (PMID 27112767, 2016). "In a competitive binding assay using Jurkat human T-cell leukemia cells and [125I]FC-131 as the radioligand, MK007 demonstrated high CXCR4 affinity with an IC50 of 10.2 ± 4.0 nM (n = 3)." (PMID 35006394, 2022). "We found that a suspension T-cell leukemia cell line Jurkat expresses high levels of SDF-1α responsive CXCR4 receptors while adherent HeyA8 ovarian cell line expresses low levels of CXCR4 and failed to respond to SDF-1α in a phospho-ERK assay." (PMID 25514788, 2014).
type 2 diabetes (9 papers, 2014 to 2023). "We demonstrated that intraperitoneal administration of the specific CXCR4 antagonist AMD3100 reversed PDN in two animal models of type II diabetes." (PMID 24961298, 2014). "We have now demonstrated that the specific CXCR4 antagonist AMD3100 reversed PDN in two animal models of type II diabetes indicating that ongoing CXCR4/SDF-1 signaling is necessary for the manifestation of PDN." (PMID 24961298, 2014). "Overall this first series of experiments demonstrated that SDF-1/CXCR4 signaling is necessary for the expression of pain hypersensitivity in two separate animal models of type II diabetes." (PMID 24961298, 2014). "A study found that CXCR4 antagonists could prevent cardiofibrosis in mice with type I and type II diabetes." (PMID 37928902, 2023). "In a very recent paper, a mid-term (4-month) treatment with sitagliptin was associated with a significant increase in EPCs -phenotypically characterised as CD34+/CXCR-4+ cells- in 30 patients with type 2 diabetes in poor glucose control with metformin and/or sulphonylurea." (PMID 28231835, 2017). "Indeed, we observed that the specific CXCR4 antagonist AMD3100 reversed PDN in two animal models of type II diabetes indicating that ongoing CXCR4/SDF-1 signaling is necessary for the manifestation of PDN." (PMID 24961298, 2014). "In order to determine whether SDF-1/CXCR4 signaling played a role in this behavior we examined the effects of blocking CXCR4 receptors on pain behavior in this model of type II diabetes." (PMID 24961298, 2014). "We now demonstrate that administration of a selective CXCR4 antagonist, AMD3100, substantially reverses neuropathic pain in animal models of type II diabetes." (PMID 24961298, 2014). "Canagliflozin when added to subjects with Type 2 Diabetes along with metformin and/or Insulin, demonstrates a functional improvement of CD34+ Endothelial Progenitor Cell migratory function through increased CD34/CXCR4 positivity." (PMID 33581737, 2021).
Cirrhosis (8 papers, 2017 to 2025). A chronic disorder of the liver in which liver tissue becomes scarred and is partially replaced by regenerative nodules and fibrotic tissue resulting in loss of liver function. "The expression of CD32, TLR4, and CXCR4 was increased in cirrhosis, whereas the expression of IFNAR, CD206, CCR5, and CCR7 was reduced." (PMID 37004869, 2023). "In response to CXCL12, cells (such as HSCs) expressing CXCR4 can participate in fibrosis and cirrhosis through migration and activation." (PMID 34386499, 2021). "To examine B cell phenotypes in D-LC caused by HBV, we performed flow cytometry using a panel of 11 markers (CD19, CD10, CD38, IgD, CD21, CD27, CCR7, CXCR3, CXCR4, CXCR5, and IL-21R) and demonstrated the changes of B cell subsets for the first time in HBV-associated advanced cirrhosis." (PMID 34248941, 2021). "Furthermore, CXCR4 expression was significantly related to the histological grade and hepatic cirrhosis (P=0.035 and 0.043, respectively)." (PMID 31534521, 2019). "We reported higher proportions of CXCR4-expressing and lower proportions of CD64- and CCR5-expressing macrophages within the entire resident macrophage population in cirrhosis." (PMID 37004869, 2023). "For instance, CXCR4 showed a strong positive correlation with activated CD4 T cells and effector memory CD8 T cells, highlighting the potential role of these cells in the immune landscape of cirrhosis." (PMID 41223189, 2025). "CXCR4 (AUC = 0.941), COL1A2 (AUC = 0.919), CCR7 (AUC = 0.878), COL1A1 (AUC = 0.853), CXCL12 (AUC = 0.848), and CXCL8 (AUC = 0.828) had similar AUC values, demonstrating that the identified hub genes exhibited a reliable discriminatory capacity as potential biomarkers for cirrhosis." (PMID 41223189, 2025). "Here, we observe a correlation between CXCR4 expression and the histological grade and hepatic cirrhosis, but not with tumor size and metastasis in HCC tissues, which could be most likely due to the low sensitivity and specificity of the CXCR4 antibody for IHC and needs to be studied in the future." (PMID 31534521, 2019).